CLDN5 (claudin 5)
Diseases named in the same sentence as CLDN5 in open-access papers (continued):
Sharing a sentence is not in itself a finding about the gene and the disease.
leukemia (3 papers, 2011 to 2021). A malignant (clonal) hematologic disorder, involving hematopoietic stem cells and characterized by the presence of primitive or atypical myeloid or lymphoid cells in the bone marrow and the blood. "Collectively, these results demonstrate that the loss of endothelial TJ proteins ZO-1, claudin-5 and occludin leaded by MMP-2 and -9 is a central event in the opening of the BBB in CNS leukemia." (PMID 21857898, 2011).
lymphocytic colitis (3 papers, 2021 to 2025). Microscopic colitis characterized by the accumulation of lymphocytes in the colonic epithelium and lamina propria. "It points to a mechanism of TNF-α-dependent decrease in claudin-5 in the colon mucosae of lymphocytic colitis patients, as TNF-α release was evident in colonic epithelial HT-29 cells following C. concisus infection." (PMID 33669494, 2021).
Obesity (3 papers, 2021 to 2025). Accumulation of substantial excess body fat. "Furthermore, single-nucleus RNA sequencing has recently revealed that endothelial cells in mice are involved in the development of obesity, thus highlighting the importance of studying the role of CLDN5 in the context of AT and obesity." (PMID 40871639, 2025). "Therefore, we examined the levels of claudin-5 (TJ protein) with brain samples and observed additive effects of AD and diet-induced obesity." (PMID 34393764, 2021).
serous ovarian adeno-carcinoma (3 papers, 2016 to 2020). "Down-regulated claudin-5 expression in tumor vessels may serve as a potential marker for poor prognosis in hepato-cellular carcinoma while increased claudin-5 expression is associated with aggressive behavior in serous ovarian adeno-carcinoma." (PMID 27398181, 2016). "At the same time a VEGF-dependent regulation of the junctional protein claudin 5 with a consecutive increase of permeability was detected in our previous studies in an in vitro corpus luteum model and in serous ovarian cancer." (PMID 26868378, 2016). "Moreover, Cldn5 overexpression correlated with aggressive behavior in serous ovarian adenocarcinoma and was shown to be involved in the malignant transformation of borderline mucinous EOC tumors." (PMID 32156068, 2020).
squamous cell carcinoma (3 papers, 2011 to 2017). A carcinoma arising from squamous epithelial cells. "For instance, CLDN5 expression was detected in most of adenocarcinomas, but squamous cell carcinomas was detected CLDN1 overexpression." (PMID 28160565, 2017).
temporal lobe epilepsy (3 papers, 2022 to 2024). A localization-related (focal) form of epilepsy characterized by recurrent seizures that arise from foci within the temporal lobe, most commonly from its mesial aspect. "For example, studies in the kainic acid model of temporal lobe epilepsy demonstrated a significant increase in claudin-5 levels 24–72 h after kainic acid injection in correspondence with neuronal injury." (PMID 35631535, 2022). "As increased claudin-5 expression and paracellular permeability were observed in a murine model of temporal lobe epilepsy, the higher claudin-5 levels and improved BBB function post anti-osteopontin IgG therapy in the current study is correlative and needs detailed investigation." (PMID 36463381, 2022).
type 2 diabetic (3 papers, 2011 to 2024). "Here, we used the type 2 diabetic rat model to induce DN and show a nephroprotective effect following the stimulation of PPAR-α, which stabilized renal tight junction components claudin-2, claudin-5, and claudin-16." (PMID 39684861, 2024).
vascular dementia (3 papers, 2022 to 2025). A degenerative vascular disorder affecting the brain. "The presence of CLDN5 in tight junction expression under RunX1 underlines its role in blood-brain barrier integrity, a key factor in vascular dementia." (PMID 41032496, 2025). "A recent study reported ROCK 1/2, and inflammatory cytokines (IL-1 and IL-6) were upregulated in vascular dementia models while the expression of claudin-5, which maintains the blood–brain barrier, and MAP2 as a nerve cell-specific factor, were decreased in the hippocampal region." (PMID 39779619, 2025). "However, expression of claudin-5, which maintains the blood–brain barrier, and MAP2 as a nerve cell-specific factor, was decreased in the hippocampal region of the vascular dementia model." (PMID 35203655, 2022). "The chosen proteins Apolipoprotein E (APOE), Amyloid Beta Precursor-Like Protein (APLP), Claudin-5 (CLDN5), Superoxide Dismutase (SOD), Matrix Metalloproteinase-9 (MMP-9), and Methylenetetrahydrofolate Reductase (MTHFR) play a key role in the progression of vascular dementia." (PMID 41032496, 2025).
Velocardiofacial syndrome (3 papers, 2013 to 2024). "Notably, the 22q11.2-deletion syndrome causes CLDN5 haploinsufficiency and leads to reduced CLDN5 levels in endothelial cells." (PMID 38476764, 2024). "CLDN5 was originally identified as one of the deleted genes in 22q11 deletion syndrome (22q11DS), also known as DiGeorge syndrome or Velocardiofacial syndrome, and was named TMVCF (transmembrane protein deleted in velocardiofacial syndrome)." (PMID 36978081, 2023).
ZIKV infection (3 papers, 2019 to 2025). "The in vitro data fully corroborated with animal experiments in which we observed that ZIKV infection downregulated the expression of claudin-5, occludin, JAM-3, and ZO-1 protein levels in Bmal1ECKO mice." (PMID 40313764, 2025). "ZIKV infection resulted in a marked decrease in claudin-5, occludin, JAM-3, and ZO-1 expression levels in these mice." (PMID 40313764, 2025). "In the next series of experiments, we focused on the impact of ZIKV infection and/or Bmal1 silencing on the expression of TJ genes and proteins, such as claudin-5, occludin, zona occludens (ZO-1), and junctional adhesion molecule-3 (JAM-3)." (PMID 40313764, 2025). "ZIKV infection significantly decreased claudin-5, occludin, and ZO-1 protein levels in cells with silenced Bmal1 gene." (PMID 40313764, 2025). "Importantly, ZIKV infection in Bmal1ECKO mice resulted in a significant decrease in the expression of claudin-5, occludin, JAM-3, and ZO-1 proteins when compared to controls." (PMID 40313764, 2025). "Importantly, these changes were consistent with the downregulation of the expression of claudin-5, occludin, and ZO-1 proteins in endothelial cells subjected to ZIKV infections and Bmal1 silencing." (PMID 40313764, 2025). "Western blot analysis also revealed that ZIKV infection induced no change in the amount of claudin-5 expressed in the placentae." (PMID 31569528, 2019).
acute liver failure (2 papers, 2013 to 2021). Rapid deterioration of liver function causing encephalopathy and coagulopathy. "Treatment with MMP-9 chelator GM6001 can reverse disruption of claudin-5 and BBB permeability in brain edema of mice with acute liver failure." (PMID 23505411, 2013). "In acute liver failure, MMP9 also degrades occludin and CLDN5 to increase vascular permeability." (PMID 33799999, 2021).
acute lung injury (2 papers, 2021 to 2023). A condition of lung damage that is characterized by bilateral pulmonary infiltrates (pulmonary edema) rich in neutrophils, and in the absence of clinical heart failure. "We previously reported that claudin-5, a tight junctional protein, mediates lung vascular permeability in a murine model of acute lung injury (ALI) induced by lipopolysaccharide (LPS)." (PMID 34571834, 2021).
acute respiratory distress syndrome (2 papers, 2016 to 2024). Progressive and life-threatening pulmonary distress in the absence of an underlying pulmonary condition, usually following major trauma or surgery. "Specific and direct targeting of claudin-5 using these approaches offers the potential of preventing acute respiratory distress syndrome, particularly in those individuals at greatest risk due to underlying alcohol abuse, by improving alveolar barrier function and fluid clearance." (PMID 27452368, 2016). "Through activation of NF-kappa-B, TNF-α suppresses the tight-junction protein claudin-5 that causes capillary leakage and massive influx of plasma proteins and white blood cells infiltrating the surrounding tissue and promotes the development of acute respiratory distress syndrome (ARDS)." (PMID 38256229, 2024).
asthma (2 papers, 2021 to 2024). "Thus, a positive correlation of asthma with systemic IL-10 and organoid expression of Tnf, Cxcl10, Cldn5, Cldn4 in the A group was found." (PMID 38255939, 2024). "Plasma levels of claudin-4 and claudin-5 were reported to be elevated in asthma patients, particularly during exacerbations, and the levels were found to correlate negatively with lung function and positively with total IgE level and the percentage of blood eosinophils." (PMID 33790367, 2021).
atrial fibrillation (2 papers, 2020 to 2025). A disorder characterized by an electrocardiographic finding of a supraventricular arrhythmia characterized by the replacement of consistent P waves by rapid oscillations or fibrillatory waves that vary in size, shape and timing and are accompanied by an irregular ventricular response. "In atrial fibrillation (AF) patients, Cldn5 expression was significantly reduced in the left atrial appendage, and accompanying proteomic analysis revealed dysregulation of proteins associated with dilated cardiomyopathy." (PMID 40940757, 2025).
cerebral amyloid angiopathy (2 papers, 2013 to 2025). "Also, amyloid-β decreases expression of claudin-5, increases activities of MMP-2, -9, causes BBB leakage and promotes BBB permeability in humans with cerebral amyloid angiopathy." (PMID 23505411, 2013).
cervical cancer (2 papers, 2021 to 2022). A primary or metastatic malignant neoplasm involving the cervix. "The exosomes of cervical cancer taken up by HUVEC cells can alter vascular integrity and facilitate metastasis through the generation of endoplasmic reticulum stress and the decrease in the expression of zonula occludens-1 (ZO-1) and claudin-5 (CLDN5) proteins, both associated with tight junctions." (PMID 34202942, 2021).
dementia (2 papers, 2021 to 2023). Loss of intellectual abilities interfering with an individual's social and occupational functions. "Complementarily to these data, we have found differential patterns of astrocytes implication in dementia using additional markers such as AQP4, GS1, GLAST1, and for ECs such as Lectin UEA, vimentin, PECAM1 and CLDN5." (PMID 34025357, 2021).
dilated cardiomyopathy (2 papers, 2016 to 2019). Cardiomyopathy which is characterized by dilation and contractile dysfunction of the left and right ventricles. "Claudin-5 has also been shown in an unbiased screen to be one of only four genes down-regulated and hyper-methylated in human dilated cardiomyopathy." (PMID 27999547, 2016).
edema (2 papers, 2013 to 2017). An abnormal accumulation of fluid beneath the skin, or in one or more cavities of the body. "Our study showed that early relief of severe bilateral carotid stenosis could lead to brain edema and elevation of BBB permeability, which was associated closely with increased activity and expression in MMP-9 and decreased quantity in tight junction proteins claudin-5 and occludin." (PMID 23469092, 2013).
encephalitis (2 papers, 2023 to 2025). An acute inflammatory process affecting the brain parenchyma. "This may be related to PI3K inhibitor LY294002 increasing the expression level of ZO-1 and Claudin-5, effectively improving BBB permeability after brain injury in mice with anti-NMDAR encephalitis and thus reducing the damage of anti-NMDAR antibody to NMDAR." (PMID 37314618, 2023).
glomerulosclerosis (2 papers, 2022 to 2025). A hardening of the kidney glomerulus caused by scarring of the blood vessels. "First, we showed that mice with podocyte-specific deletion of Cldn5 manifested albuminuria but not glomerulosclerosis, as least within our observation period." (PMID 35332151, 2022).
Hearing impairment (2 papers, 2014 to 2022). A decreased magnitude of the sensory perception of sound. "Downregulations in claudin-5 and occludin expression were associated with increased BLB permeability in the pathology of noise-induced hearing impairments, although the mechanism remains poorly understood." (PMID 35496913, 2022). "All these findings suggest that both decrease of Claudin-5 and Occludin and increased BLB permeability are involved in the pathologic process of noise-induced hearing impairment; however, the causal relationship and underlying mechanisms should be further investigated." (PMID 25539640, 2014). "All these findings suggest that Claudin-5 and Occludin are involved in the noise-induced BLB ultrastructure changes, increased BLB permeability and the hearing impairment." (PMID 25539640, 2014).
Heat Stroke (2 papers, 2017 to 2018). A condition caused by the failure of body to dissipate heat in an excessively hot environment or during PHYSICAL EXERTION in a hot environment. "Lastly, in the setting of fatal heat stroke, serum claudin-5, ZO-1, and occludin levels are unchanged." (PMID 30259344, 2018). "Relative mRNA quantification using Taqman real-time PCR assay demonstrated increased calibrated normalized relative quantity (CNRQ) values of MMP9, CLDN5, OCLN, ZO1 and AQP4 in heat stroke cases." (PMID 28490769, 2017). "Heat stroke cases showed an increase in brain water content, which was found to be positively correlated with MMP9, OCLN, ZO1 and CLDN5 mRNA." (PMID 28490769, 2017). "When those four validated reference genes, SDHA, POLR2A, IPO8 and HMBS, were used for normalization, increased cerebral expressions of AQP4, CLDN5, OCLN, ZO1 and MMP9 were detected in heat stroke group." (PMID 28490769, 2017). "The present study, for the first time, reports increased cerebral MMP9, CLDN5, OCLN, ZO1 and AQP4 in heat stroke and suggest a crucial role of reference gene selection when using postmortem human tissues." (PMID 28490769, 2017). "However, in the present study, increased CLDN5, OCLN and ZO1 mRNA expression was detected in the heat stroke group." (PMID 28490769, 2017).
Huntington disease (2 papers, 2022). Huntington disease (HD) is a rare neurodegenerative disorder of the central nervous system characterized by unwanted choreatic movements, behavioral and psychiatric disturbances and dementia. "In addition, reduced Claudin-5 gene and protein in the ChP was also detected in AD patients and Huntington’s disease patients." (PMID 35413993, 2022).
lung diseases (2 papers, 2022 to 2023). "The expression profile of Claudin-5 and the other members of the Claudin family changes in several lung diseases associated with edema." (PMID 36620216, 2022). "The expression levels of Cldn5 were significantly decreased in various lung diseases, such as Covid‐19,111 chronic obstructive pulmonary disease, and lung injury, which induced damage to the pulmonary endothelial barrier." (PMID 37249284, 2023).
memory impairment (2 papers, 2022 to 2024). "In animal behavior tests, we found that, while elder mice exhibited learning and memory impairment, intravenous injection of claudin-5 can ameliorate this impairment in elder mice." (PMID 35471411, 2022).
meningitis (2 papers, 2020). A disorder characterized by acute inflammation of the meninges of the brain and/or spinal cord. "Several BBB junction molecules were found to be downregulated in meningitis including occludin, claudin-5 and ZO-1, highlighting the BBB breakdown." (PMID 32529267, 2020). "The changes in Cdh5 and Cldn5 expression observed in the present study are consistent with the previous findings reported in a Staphylococcus aureus and group B Streptococcus model of meningitis." (PMID 32509459, 2020).
mesothelioma (2 papers, 2012 to 2024). A usually malignant and aggressive neoplasm of the mesothelium which is often associated with exposure to asbestos. "Such variations in sample sizes can influence the detection and reporting of low-frequency markers like claudin-5 in mesothelioma, leading to differing conclusions in otherwise similar studies." (PMID 39364319, 2024).
metastatic disease (2 papers, 2012 to 2021). "As expected, claudin-5 presented a normal distribution forming a continuous line at the cell–cell contacts in controls; however, as the metastatic disease progressed, this TJ protein showed an irregular and discontinuous distribution." (PMID 33671551, 2021).
oral squamous cell carcinoma (2 papers, 2016 to 2022). "No study, to the best of our knowledge shows the association of claudin-5, claudin-7 together with occludin expression in oral squamous cell carcinoma (OSCC) and their clinic-pathological prognostic factors." (PMID 27398181, 2016). "The objective of this study was to investigate the expression of claudin-5, claudin-7 and occludin in oral squamous cell carcinoma (OSCC) and their relationships with the prognostically-related clinico-pathologic features." (PMID 27398181, 2016).
pancreatic adenocarcinoma (2 papers, 2017 to 2023). "We also observed differential methylation of RMRM (reprimo), CLDN5, LHX1, NTPX2, SPARC and ST14, which are already reported as aberrantly methylated genes in pancreatic adenocarcinoma." (PMID 28423671, 2017).
preeclampsia (2 papers, 2022 to 2025). Preeclampsia is a hypertensive disorder of pregnancy that is characterized by new-onset hypertension with proteinuria presenting after 20 weeks of gestation, and depending on mild or severe forms may initially present with severe headache, visual disturbances, and hyperreflexia. "In this manuscript, we report a reduction in the availability of claudin-5 in the cell membrane of brain endothelial cells exposed to plasma from women with preeclampsia." (PMID 35269411, 2022). "This suggests that, while EVs can deliver Cldn5 in immune-driven neuroinflammation, they can also deplete or redistribute Cldn5 in systemic disorders, such as preeclampsia, suggesting context-specific, bidirectional regulation of endothelial barrier integrity via EVs." (PMID 40940757, 2025).
pulmonary edema (2 papers, 2019 to 2024). Accumulation of fluid in the lung tissues causing disturbance of the gas exchange that may lead to respiratory failure. "Stimulation of mouse lungs with LPS can increase pulmonary microvascular permeability through a process associated with tight junction proteins such as Occludin, Claudin-5, and zonula occluden-1 (ZO-1), leading to pulmonary oedema in mice." (PMID 38802896, 2024). "Decreased expression of VE-cadherin, Occludin, Claudin-5, and ZO-1 can significantly increase endothelial permeability, cause pulmonary edema, and aggravate lung injury.VE-cadherin can further enhance tight junction formation by promoting the expression of Claudin-5." (PMID 30867053, 2019). "However, the expression levels of VE-Cadherin, Occludin, Claudin-5, and ZO-1 were significantly increased after treatment with BMSCs, showing that BMSCs might reduce pulmonary edema by strengthening the adhesion and tight junction between cells." (PMID 30867053, 2019).
pulmonary fibrosis (2 papers, 2020). Chronic progressive interstitial lung disorder characterized by the replacement of the lung tissue by connective tissue, leading to progressive dyspnea, respiratory failure, or right heart failure. "Downregulation of CLDN5 was associated with disrupted endothelium tight junctions in bleomycin-induced pulmonary fibrosis, and which may be involved in epithelial-mesenchymal transition (EMT)." (PMID 33119648, 2020).
relapse-remitting MS (2 papers, 2015 to 2017). "We also found that the degree of claudin-5 disorganization was positive correlated with the clinical scores, which is similar to the modification of claudin-5 in relapsing-remitting MS patients." (PMID 28596825, 2017).